CASP1 (caspase 1)
Diseases named in the same sentence as CASP1 in open-access papers (continued):
Sharing a sentence is not in itself a finding about the gene and the disease.
infection (continued). "Furthermore, Asc-deficient macrophages were not able to process caspase-1 upon OT infection, evidenced by the absence of active caspase-1 by western blotting analysis and flow cytometric analysis using an active caspase-1-specific fluorescent probe (FAM-YVAD-FMK)." (PMID 22723924, 2012). "Therefore, the findings of this study suggest that previous effects of AbM that were observed against tumors and infection may be attributed to the ability of AbM to both enhance IL-1β transcription and stimulate NLRP3 inflammasome-dependent caspase-1 activation." (PMID 22844468, 2012). "The analysis showed that neither the caspase-1 inhibitor YVAD, the cathepsin B inhibitor CA-074Me, nor the pan-caspase inhibitor ZVAD had any significant effect on DNA fragmentation, loss of mitochondrial potential or compromised plasma membrane integrity after two days of infection." (PMID 21637850, 2011). "In contrast, Pam3CSK4-primed CASP1-/- THP-1 cells released negligible levels of inflammasome-dependent cytokines and did not undergo substantial cell death upon infection." (PMID 40162563, 2025). "Our findings showed that, at baseline and regardless of the type of infection, patients exhibited reduced ASC speck-positive monocytes and decreased activated caspase-1 in PMN compared to healthy volunteers." (PMID 38140660, 2023). "Increases in high molecular weight caspase-1 were significant for the GB590, GB653, and GB20 strains at 24 hours, but not at 48 hours post-infection." (PMID 37928185, 2023). "Infection increased serum IL-6 and IFN-γ and tissue caspase-1 but not NLRP3 in P2X7−/− mice compared to WT mice." (PMID 36831091, 2023). "Having determined that culture media of WT and Casp1-/- neutrophils lacked spontaneous LDH release during the first 4–5 hours, we next performed infections within the first 3–4 hours in order to avoid confounding effects of spontaneous LDH release." (PMID 35849616, 2022). "Caspase-1 and NLRP3 inhibitors blocked inflammasomes in vitro but did not impact macrophage infection, measured as mNG+ macrophage frequency, and reduced the inflammatory response to infection." (PMID 35483404, 2022). "Unlike the pattern observed in the liver, only splenic caspase-1, IL-1β, and GSDMD increased during S. mansoni infection; whereas levels of NLRP3 and IL-18 did not increase during infection." (PMID 34161342, 2021). "Clones of DH82 cells lacking the caspase-1/-4 gene showed similar responses (cell death and IL-1β production) to WT DH82 cells after infection with S. Typhimurium, or stimulation with NLRP3-activating concentrations of nigericin." (PMID 34433041, 2021). "We found that WT BMDMs produced IFN-β in response to HSV1 (MOI, 10; 6 h post-infection) or F. novicida infection (MOI, 1; 3 h post-infection), while Aim2–/–, Asc–/– and Casp1–/– BMDMs did not." (PMID 34471287, 2021). "Bt infected wildtype keratinocytes were observed to have fewer infected cells and lower total area of infection as compared to infected ASC KO and CASP1 KO cells, although it was not statistically significant." (PMID 34821529, 2021). "Surprisingly, caspase-1 activity in the infiltrating CD11b+ leukocyte populations from both WT and ASC-/- mice did not increase during infection." (PMID 33524073, 2021). "Although MT3 exerted disparate effects on caspase-11 activation in gram-positive and gram-negative infections, caspase-1 and IL-1β activation was suppressed by MT3 in both infection settings." (PMID 34867993, 2021). "Notably, in high‐dose infection (YM = 1), STING‐ and Caspase1‐mediated signalling contributed equally to induce Socs1 expression, but diverse type I IFN production, which may arise from earlier onset time of Socs1 mRNA triggered by STING‐mediated pathway than Casp1‐dependent signalling." (PMID 32885594, 2020).
infection (continued). "Experiments in caspase-11-deficient primary macrophages showed that caspase-11 did not contribute to MNV-induced caspase-1 activation and that the latter was sufficient for mediating IL-1β maturation and secretion upon MNV infection." (PMID 31017981, 2019). "As a consequence, the absence of ASC or Casp1/11, but not NLRP3, also resulted in elevated T. gondii dissemination during the acute stage of infection, as indicated by an increased pathogen burden in the liver and spleen of the infected mice." (PMID 31194844, 2019). "The amniotic fluid concentrations of some inflammasome mediators (CASP1, IL1B, NLRP3, and IL18) are greater in women who have spontaneous preterm or term labor with intraamniotic infection/inflammation than in those without this clinical condition." (PMID 30935390, 2019). "Nevertheless, the control of the parasite burden during the chronic stage of the infection in the brain did not require NLRP3, ASC, or Casp1/11." (PMID 31194844, 2019). "After intratracheal infection with this pathogen, CFU counts in lungs and/or BALF were higher in mice lacking caspase-1, AIM2 or NLRP3 compared to C57BL/6 controls." (PMID 30456207, 2018). "We have not found any evidence of neutrophil cell death during infection of larvae with ST, being this in agreement with a recent study reporting that neutrophils do not undergo pyroptotic cell death on NLRC4 and caspase-1 activation." (PMID 27363812, 2016). "Collectively, these results suggest that infection with GBS triggers, in neutrophils, pro-IL-β processing and IL-β secretion via a mechanism that largely depends on caspase-1, but not on caspase-8 or on serine proteases." (PMID 27509078, 2016). "Analysis of the activity of several caspases that lie upstream of caspase-3, using cell lysates from infected cultures at 5 h p.i., demonstrated no significant caspase-1, -8 or -9 activity following UPSA 807 infection (data not shown)." (PMID 27383371, 2016). "Although YopM inhibits a pathway dependent on Asc and caspase-1, we observed no decrease of IL-1β in cells lacking NLRP3, NLRC4, or caspase-11 compared to wild-type cells after infection with Y. pestis lacking YopM." (PMID 27911947, 2016). "Our in vitro infection data suggest that Ft-induced BMDM cell death is non-apoptotic (Caspase-3 independent), non-pyroptotic (Caspase-1-independent), and non-pyronecrotic (Asc-independent)." (PMID 27926940, 2016). "We also found evidence that the attenuation of infection was mediated by protective mechanisms induced by the anti-viral, pro-inflammatory cytokines IFN-α and TNF-α, but not caspase-1." (PMID 25061945, 2014). "Not surprisingly, infection conditions, including MOI, can affect the detection of caspase-1 activation in response to L. pneumophila, as higher MOIs likely enhance the number of macrophages that harbor bacteria." (PMID 24409420, 2013). "Our collective findings from the infection with WT bacteria suggest that NLRP3, but not NLRC4, plays a major role in inducing caspase-1 activation." (PMID 23357873, 2013). "Within 2 hrs of infection at low MOI, no more than 2% of infected macrophages lacking caspase-1, -7 or functional Naip5 were TUNEL positive whereas 20% infected wild-type macrophages were apoptotic." (PMID 19343209, 2009). "However, in Aim2–/– pBMDMs, there was a complete absence of activation of pyroptotic molecules, including CASP1 and gasdermin D (GSDMD), upon MPXV infection." (PMID 41225161, 2025). "Simultaneously, AjCASP-1 activity was significantly upregulated after AJ01 infection, which could be inhibited by 25 μm of Z-YVAD-FMK (CASP-1-specific inhibitor) without reduce coelomocyte viability in the uninfected coelomocytes." (PMID 40085533, 2025). "The pharmacological inhibition of caspase-1 using YVAD inhibitor in Caco-2 and ACE2-A549 cells reduced SARS-CoV-2 infection, as revealed by the frequency of spike (S)-positive cells at 24 hours after infection, without affecting cellular viability." (PMID 37920468, 2023).
infection (continued). "In addition, NLRP3 and CASP1 expression was increased at low MOI in both strains, while IL-1β was independent of virulence but dependent on infection MOI, suggesting the activation of pyroptosis." (PMID 35631013, 2022). "Furthermore, in a S. aureus craniotomy biofilm infection model, TLR2, but not TLR9, was critical for host bacterial containment through the caspase-1-mediated activation of IL-1β, which was reduced in the Tlr2−/− mice." (PMID 36226943, 2022). "Intriguingly, infection of the ExoU-L618-expressing PMVECs with the PA103 mutant lacking ExoU and ExoT triggered robust caspase-1 activation, indicating that other bacteria-associated factors are also involved in caspase-1 activation during P. aeruginosa infection." (PMID 35202178, 2022). "Caspase-1 activity in ASC-/- microglia was not completely abrogated, suggesting that ASC-independent non-canonical inflammasome pathways are also activated during infection." (PMID 33524073, 2021). "In contrast, treatment with poly(dA:dT) allowed interactions between endogenous ASC, AIM2 and caspase-1, but not Pyrin, ZBP1, caspase-8, RIPK3, RIPK1 or FADD, suggesting that infection has a distinct ability to form this AIM2 multi-protein cell death-inducing complex." (PMID 34471287, 2021). "Interestingly, NLRP3 deficiency resulted in higher levels of IL-1β in the brain later in infection, suggesting a regulatory role for NLRP3 in modifying caspase-1 activity rather than simply increasing IL-1β activation in response to an immune stimulus." (PMID 33524073, 2021). "We found that infection with wild type bacteria and fliI mutants (that express cytosolic flagellin, but do not assembly the flagellum), but not with flaA mutants, triggers robust CASP8 activation in Casp1/11–/–and Gsdmd–/–macrophages." (PMID 31251782, 2019). "Confirming our previous experiments, L.g.+ infection induced increased ear thickness compared with L.g.− in C57BL/6, but not in Nlrp3−/−, Asc−/−, Casp1−/− or Tlr3−/− mice." (PMID 31754185, 2019). "We observed robust IL-1β production in BMDMs from WT and Aim2–/–mice in response to infection with MAYV, but Nlrp3–/–, Asc–/–and Casp1/11–/–macrophages failed to induce IL-1β secretion." (PMID 31479495, 2019). "Interestingly, ΔYopM infection in BMDMs failed to upregulate NLRP3 and HMGB1 secretion, but significantly induced caspase-1 activation and IL-1β secretion." (PMID 27929533, 2016). "When cells are not pretreated with ATP, infection with P. gingivalis in this model does not trigger the activation of the NLRP3 inflammasome complex, including NLRP3, ASC and caspase-1, until P. gingivalis LPS stimulation, even though in a short time 2 h (except caspase-1)." (PMID 26511096, 2015). "Therefore, much like the pathways described for Mtb, if inflammasome-independent IL-1α can be generated during infection, adaptive immunity should be minimally impacted in the absence of NLRP3, ASC, or caspase-1." (PMID 24409181, 2013). "The pronounced deficiency in IFN-γ production exhibited by MyD88−/− cells, but not by NLRP3−/− and caspase-1−/− cells, could explain this difference, as IFN-γ−/− mice also succumb early to infection." (PMID 24098823, 2013). "However, unlike the MyD88−/− and IFN-γ−/− mice, which succumbed to infection, the NLRP3−/− and caspase-1−/− mice survived infection." (PMID 24098823, 2013). "Interestingly, TLR2−/− macrophages did undergo inflammasome-dependent cell death after F. novicida infection, in contrast to ASC−/−, caspase-1−/−and AIM2−/− macrophages, which do not die up to 14 h post-infection (and data not shown)." (PMID 21698237, 2011). "This difference in response may be due to the dynamic and evolving nature of IFN-γ production at this site of infection, suggesting 8 dpi may not be the optimal time where caspase-1 impacts peritoneal IFN-γ production or alternatively caspase-1 is not necessary for peritoneal IFN-γ production." (PMID 39446964, 2024).
infection (continued). "The relative expression levels of the necrotic factors Caspase-1, Caspase-3, NLRP3, and IL-1β proteins in placental nourishing cells were higher in patients with multiple genital tract infections compared to those with single infections or no infections in the PROM group (P < .05)." (PMID 38115314, 2023). "Treatment with the caspase 1-specific inhibitor Y-VAD decreased IL-1β secretion for both strains from 4629.3 pg/mL (without Y-VAD) to 1294.3 pg/mL (with Y-VAD) during the infection with the NADL cp strain and from 252.9 pg/mL (without Y-VAD) to 63.5 pg/mL (with Y-VAD) with the NY-1 ncp strain." (PMID 37515181, 2023). "Importantly, caspase-1 activation was also reduced by ~50% in pearl DCs after STm infection, as measured by the percentage of cells labeled by the fluorescent active caspase-1 probe FAM-YVAD-FMK (FLICA), despite no reduction in pro-caspase-1 expression in these cells." (PMID 29253868, 2017). "However, excluding a significant, but seemingly unnecessary increase in IL-17 levels at day 1 post-infection in Nlrp3-/- mice, differences in the level of KC or MCP-1 that might impact myeloid cell recruitment were not discernable between Nlrp3-/-, Asc-/-, Casp1/11-/- and Aim2-/- mice." (PMID 27926940, 2016).
tumor (377 papers, 2001 to 2026). "CAR T cell-induced pyroptosis further illustrates this complexity: granzyme B activates caspase-3 and GSDME in tumor cells, which triggers caspase-1-dependent GSDMD in macrophages, causing cytokine release syndrome." (PMID 41291696, 2025). "In the pan-tumor analysis, CASP1 expression was slightly upregulated in most solid tumors relative to normal tissues, suggesting that the potential function of CASP1 associated with tumor inflammatory vesicle activation and apoptosis is prevalent." (PMID 40535567, 2025). "While curdione and borneol inhibited inflammatory factors such as IL-6 and IL-1β expression in macrophages, TNF-α and CASP1 mRNA expression levels were up-regulated, which are associated with anti-tumor and anti-viral responses." (PMID 39911394, 2025). "In Caspase-1–deficient mice, enhanced tumor formation resulted in intrinsic changes in epithelial gene-expression programming affecting proliferation and apoptosis." (PMID 39684769, 2024). "On the other hand, the administration of PTX to tumor cells caused a significant increase in caspase-1 activity compared to untreated tumor cells (p < 0.01)." (PMID 39433537, 2024). "In an azoxymethane (AOM)-DSS mice model with reduced NLRC4 activity and deficient for caspase-1, a significant increase in tumor development and aggressiveness was observed compared to the increase seen in wild type mice." (PMID 39684769, 2024). "Activated caspase 1 also cleaves and activates IL-1 family cytokines, which have been shown to promote tumor-associated inflammation." (PMID 38898209, 2024). "Tumor-associated macrophages are involved in pyroptosis through the classical pathway induced by the caspase-1 cleavage of GSDMD and the pathway mediated by the caspase-8 cleavage of GSDME and the granzyme action of GSDMB." (PMID 37542283, 2023). "Reduction of intestinal IL-18 levels in NLRP3 and caspase-1-deficient mice exposed to AOM/DSS showed that recombinant IL-18 prevented tumor development." (PMID 37081882, 2023). "Caspase-1 cleaves peroxisome proliferator-activated receptor gamma (PPARγ), which limits FA oxidation, thereby accumulating lipid droplets and promoting tumor-associated macrophage differentiation." (PMID 37426676, 2023). "CASP1-deficient mice showed enhanced colon epithelial and tumor proliferation, indicating its role as a tumor-suppressor protein." (PMID 38283944, 2023). "Caspase-1 deficiency significantly impaired tumor growth, underlining the importance of this pathway for tumor promotion by TAMs." (PMID 35954274, 2022). "In the tumor-draining lymph node of mice, Tmem176b deletion was associated with increased Caspase-1 activation in CD11b+ cDCs (cDC2) as well as with increased CD4+ RORγT+ cells versus WT animals." (PMID 36340035, 2022). "ROS have been reported to induce tissue damage, to elicit anti-tumor immune response, to cause cell death via caspase 1, 3 and 8 pathways." (PMID 35978820, 2022). "IFN-γ can cause tumor cell apoptosis by increasing caspase-1, -3, -8 expression in the cells: It also upregulates secretion of FAS and FAS ligand and TNF-related apoptosis-inducing ligand (TRAIL)." (PMID 33777767, 2021). "miR-190 is involved in the regulation of several tumor suppressor genes, including CASP1, IFI6, IFITM2 and OAS1, which are associated with the induction of cell apoptosis and interferon response pathways." (PMID 37304648, 2021). "A recent study demonstrated that the downregulation of caspase-1 in breast cancer cells was significantly associated with increased tumour proliferation and invasion, and decreased apoptosis." (PMID 33918087, 2021). "In vivo, the loss of NLRP3 inflammasome or caspase-1 activity has been found to inhibit the priming and activation of CTLs, thereby significantly blocking the cytotoxic effects of CTLs against tumour cells in mouse models." (PMID 33918087, 2021). "In tumor-bearing mice, its deficiency leads to increased activation of caspase-1 and IL-1β production by DCs." (PMID 32635472, 2020).